THA1P (threonine aldolase 1, pseudogene)
Synonyms: GLY1
Gene: Transcribed unitary pseudogene on chromosome 17 (78,248,493 to 78,254,416, reverse strand). Ensembl gene ENSG00000267676.
Diseases named in the same sentence as THA1P in open-access papers:
THA1P is named in the same sentence as 5 diseases in open-access papers, as found by Europe PMC text mining. Sharing a sentence is not in itself a finding about the gene and the disease.
THA1P shares sentences with these, for which no sentence is quoted: infection (2 papers); colitis (1); inflammatory bowel disease (1); multiple sclerosis (1); rheumatoid arthritis (1).